MUS81 (MUS81 structure-specific endonuclease subunit)
Description:
Catalytic subunit of two functionally distinct, structure-specific, heterodimeric DNA endonucleases MUS81-EME1 and MUS81-EME2 that are involved in the maintenance of genome stability. Both endonucleases have essentially the same substrate specificity though MUS81-EME2 is more active than its MUS81-EME1 counterpart. Both cleave 3'-flaps and nicked Holliday junctions, and exhibit limited endonuclease activity with 5' flaps and nicked double-stranded DNAs. MUS81-EME2 which is active during the replication of DNA is more specifically involved in replication fork processing. Replication forks frequently encounter obstacles to their passage, including DNA base lesions, DNA interstrand cross-links, difficult-to-replicate sequences, transcription bubbles, or tightly bound proteins. One mechanism for the restart of a stalled replication fork involves nucleolytic cleavage mediated by the MUS81-EME2 endonuclease. By acting upon the stalled fork, MUS81-EME2 generates a DNA double-strand break (DSB) that can be repaired by homologous recombination, leading to the restoration of an active fork. MUS81-EME2 could also function in telomere maintenance. MUS81-EME1, on the other hand, is active later in the cell cycle and functions in the resolution of mitotic recombination intermediates including the Holliday junctions, the four-way DNA intermediates that form during homologous recombination.
Synonyms: FLJ44872; SLX3
Tractability: Small molecule: a structure with a bound ligand is known; a high-quality ligand is known; it has a binding pocket of medium quality. PROTAC: ubiquitination databases record sites on it; a small molecule that binds it is known.
Gene: Protein-coding gene on chromosome 11 (65,857,126 to 65,867,653, forward strand). Ensembl gene ENSG00000172732.
Subcellular location: Nucleus, nucleolus
Subcellular location (Human Protein Atlas): Nucleoli fibrillar center; Nucleoplasm
Pathways (Reactome):
DNA Repair: Fanconi Anemia Pathway; Resolution of D-loop Structures through Holliday Junction Intermediates
Gene Ontology:
Molecular function: 3'-flap endonuclease activity; crossover junction DNA endonuclease activity; DNA endonuclease activity; endonuclease activity; protein binding; DNA binding
Biological process: DNA catabolic process; DNA repair; double-strand break repair; osteoblast proliferation; replication fork processing; resolution of mitotic recombination intermediates; response to intra-S DNA damage checkpoint signaling; telomere maintenance; double-strand break repair via break-induced replication; mitotic intra-S DNA damage checkpoint signaling; resolution of meiotic recombination intermediates; DNA recombination
Cellular component: chromosome, telomeric region; endodeoxyribonuclease complex; fibrillar center; Holliday junction resolvase complex; nuclear replication fork; nucleus; replication fork; nucleoplasm; nucleolus
Genetic constraint (gnomAD): Loss-of-function variants: 69 observed, 75.52 expected, observed/expected ratio (o/e) 0.91, 90% interval 0.75 to 1.12. The upper end of that interval is the gene's LOEUF score, 1.12, which puts it in group 4 of 6, group 1 being the genes least tolerant of losing a copy. Missense variants: 711 observed, 731.1 expected, observed/expected ratio (o/e) 0.97, 90% interval 0.91 to 1.03. Synonymous variants: 303 observed, 300.27 expected, observed/expected ratio (o/e) 1.01, 90% interval 0.92 to 1.11.
Homologues: Orthologues: chimpanzee MUS81 (99% identical), macaque MUS81 (97% identical), pig MUS81 (87% identical), guinea pig MUS81 (85% identical), mouse Mus81 (82% identical), rat Mus81 (82% identical), dog MUS81 (78% identical), zebrafish mus81 (51% identical), tropical clawed frog mus81 (50% identical), Drosophila melanogaster mus81 (31% identical), Caenorhabditis elegans mus-81 (20% identical).
Diseases named in the same sentence as MUS81 in open-access papers:
MUS81 is named in the same sentence as 39 diseases in open-access papers, as found by Europe PMC text mining. Sharing a sentence is not in itself a finding about the gene and the disease. The quoted sentences say what the papers report.
prostate carcinoma (11 papers, 2015 to 2023). A carcinoma that arises from epithelial cells of the prostate gland. "Loss of MUS81 leads to the attenuation of STING-dependent type I interferon expression in prostate cancer cells." (PMID 33490069, 2020). "Both the number of nuclear MUS81 foci and the amount of cytoplasmic dsDNA increased in parallel from hyperplasia to clinical stage II prostate cancer and decreased in stage III." (PMID 37354378, 2023). "In prostate cancer cells, MUS81 is responsible for cytoplasmic single‐stranded DNA (ssDNA) that is detected by the cGAS‐STING pathway, and is responsible for interferon induction that can recruit macrophages to control tumour growth." (PMID 31044505, 2019). "Mus81−/− mice have a predisposition to the development of spontaneous lymphomas, breast cancer and prostate cancer compared to haploinsufficient Mus81 mice." (PMID 26415217, 2015). "Moreover, the MUS81–STING axis is responsible for a prostate cancer cell-specific T-cell response in mice, thus highlighting a likely role for MUS81 in promoting antitumor immunity." (PMID 33888558, 2021). "However, there is also evidence that cytosolic DNA generated by MUS81 in prostate cancers stimulate immune response, potentially contributing to host rejection of cancer cells." (PMID 30558228, 2018). "Cleavage of genomic DNA by the DNA structure-specific endonuclease MUS81 and the PARP-dependent DNA repair pathway induces the accumulation of cytoplasmic DNA in prostate cancer cells." (PMID 37354378, 2023). "Genomic DNA cleavage by the MUS81 and PARP dependent DNA repair pathways leads to the accumulation of cgDNA in prostate cancer cells." (PMID 29867148, 2018). "In this study, we observed that MUS81 knockdown led to the accumulation of cytosolic DNA and STING pathway activation in gastric cancer, which was contrary to the previously reported phenotype in prostate cancer." (PMID 34625086, 2021). "Further findings suggest the possibility that release of MUS81-induced cytosolic DNA by prostate cancer cells contributes to STING activation, where such fragments might be a by-product of MUS81-mediated replication fork processing in these cells." (PMID 28279982, 2017). "In particular, the actions of the structure-specific endonuclease MUS81 can bring about the accumulation of cytosolic DNA via MUS81-dependent cleavage of stalled replication forks, leading to cGAS/STING activation and induction of type I IFNs, as observed in various prostate cancer cell lines." (PMID 33888558, 2021).
gastric cancer (8 papers, 2016 to 2025). A primary or metastatic malignant neoplasm involving the stomach. "Overall, these data represented excellent antitumor efficacy of talazoparib in the MUS81-deficient gastric cancer xenograft model." (PMID 35480096, 2022). "Talazoparib showed outstanding anticancer effect in the MUS81-deficient gastric cancer model; the antitumor effect was most significant after 21 d of treatment." (PMID 35480096, 2022). "Therefore, MK1775 can potentiate the anticancer effect of immune checkpoint blockade therapy by activating cGAS/STING signaling, especially in MUS81-deficient gastric cancer cells." (PMID 37354378, 2023). "MUS81 silencing gene made mice susceptible to spontaneous tumors, and the expression of MUS81 decreased in liver cancer, colorectal cancer, and gastric cancer as well as high malignant astrocytoma, which linked to tumor stage, grade, metastasis, and prognosis." (PMID 35910852, 2022). "The current study also confirmed that MUS81 knockdown reversed G2-M block caused by talazoparib in gastric cancer, which might cause tumor cells to continue mitosis with unrepaired DNA and eventually lead to cell death." (PMID 35480096, 2022). "Furthermore, MUS81 inhibition increases replication stress and impairs replication stress-associated DNA repair, thereby accumulating cytosolic DNA in gastric cancer cells and activating cGAS/STING signaling." (PMID 34625086, 2021). "We found that MK1775 and ICB combination treatment significantly elevated CD8+ T cell infiltration and perforin expression in the MUS81 deficient gastric cancer immune proficient mouse model compared to other groups, indicating increased cytotoxic T cells in the tumor microenvironment." (PMID 34625086, 2021). "Thus, the WEE1 inhibitor MK1775 specifically enhanced the anticancer effect of immune checkpoint blockade therapy in MUS81 deficient gastric cancer cells." (PMID 34625086, 2021). "In the current study, we demonstrated that MK1775 increased the accumulation of cytosolic dsDNA and activation of TBK1 phosphorylation in MUS81-deficient gastric cancer cells, indicating that MK1775 could activate the innate immune response via the cGAS/STING pathway." (PMID 34625086, 2021). "Expression of the DNA endonuclease Mus81 positively correlated with ZEB1 expression in gastric cancer, and Mus81 promotes gastric metastasis by regulating the ZEB1 transcription." (PMID 40092690, 2025). "In a recent study, MUS81 inhibition enhanced the sensitivity of the anticancer effect of the WEE1 inhibitor MK1775 in gastric cancer in vitro and in vivo." (PMID 37354378, 2023). "MUS81 overexpression has been proposed to contribute to the tumorigenesis and metastasis of gastric carcinoma." (PMID 36802409, 2023). "In LV-Ctrl gastric cancer cells, combined MUS81 and AZD5153 treatment achieved the same antitumor effect as MUS81 knockdown combined with talazoparib treatment." (PMID 35480096, 2022). "Using TCGA database, the differential expression of DNA damage repair network-related molecules was analyzed in 18 common malignant tumors; MUS81 was significantly highly expressed in gastric cancer." (PMID 35480096, 2022). "MUS81 knockdown enhanced the cytotoxic effects of talazoparib-induced apoptosis in gastric cancer cells." (PMID 35480096, 2022). "Overall, these findings indicated that sensitivity of gastric cancer to talazoparib relied on MUS81 inactivation." (PMID 35480096, 2022). "In the present study, MUS81 was involved in DNA damage repair and cell cycle regulation pathways in gastric cancer." (PMID 35480096, 2022). "Our previous research has shown that AZD5153, a novel BRD4 inhibitor, downregulates MUS81 expression, and reduces the migration of gastric cancer cells in vitro and in vivo." (PMID 35480096, 2022). "In conclusion, MUS81 was overexpressed in gastric cancer cells and was closely related to cell cycle regulation and DNA damage repair pathways." (PMID 35480096, 2022).
gastric cancer (continued). "Our previous study suggested that MUS81 was overexpressed and its high expression was positively correlated with gastric cancer metastasis." (PMID 35480096, 2022). "Our study found that high MUS81 expression indicates poor prognosis in gastric cancer and that targeting MUS81 elevates the expression of WEE1 owing to the disruption of β-TRCP-induced ubiquitination." (PMID 34625086, 2021). "We then screened the genes related to DDR among the DEGs, further analyzed changes in their expression, and found that MUS81 was significantly overexpressed in patients with gastric cancer." (PMID 34625086, 2021). "As expected, we observed an elevated cytosolic dsDNA accumulation in MUS81 knockdown gastric cancer cells." (PMID 34625086, 2021). "Patients with gastric cancer with higher MUS81 levels had a poorer prognosis than patients with lower MUS81 expression." (PMID 34625086, 2021). "Eventually, WEE1 inhibition triggers gastric cancer cell-intrinsic innate immunity through the activation of the cGAS/STING pathway, and thus, potentiates the anticancer effect of ICB therapy in MUS81 deficient gastric cancer cells." (PMID 34625086, 2021). "Based on the critical role and prognostic value of MUS81 in gastric cancer, we attempted to detect the signaling regulation network of MUS81." (PMID 34625086, 2021). "To further confirm the sensitization effect of MUS81 targeting, we generated the MUS81 knockdown and parental xenograft gastric cancer models." (PMID 34625086, 2021). "Thereafter, the cGAS/STING pathway was evaluated, and the therapeutic value of MUS81 for immunotherapy of gastric cancer was determined." (PMID 34625086, 2021). "We also found that MK1775 triggered the phosphorylation of TBK1 efficiently in MUS81 knockdown gastric cancer cells." (PMID 34625086, 2021). "Importantly, AZD5153 enhanced the talazoparib antitumor effect in gastric cancer cells by reducing MUS81 expression." (PMID 35480096, 2022). "Moreover, MUS81 was a key molecule that enhanced the talazoparib antitumor effect in gastric cancer cells." (PMID 35480096, 2022). "Our previous research showed that MUS81 was overexpressed in gastric cancer cells and might promote gastric cancer cell invasion and metastasis." (PMID 35480096, 2022). "Furthermore, it was observed that AZD5153 sensitized the anticancer effect of talazoparib in gastric cancer via down-regulating the expression of MUS81." (PMID 35480096, 2022). "MUS81 knockdown pushed gastric cancer cells with talazoparib-induced DNA damage into mitosis." (PMID 35480096, 2022). "Therefore, in this study, the Cancer Genome Atlas (TCGA) data were analyzed and showed that MUS81 is a key regulator of cell cycle distribution and DNA damage repair in gastric cancer." (PMID 35480096, 2022). "Taken together, talazoparib in combination with AZD5153 may be a promising treatment strategy for MUS81 overexpressed gastric cancer." (PMID 35480096, 2022). "Moreover, addition of the bromodomain-containing protein 4 inhibitor AZD5153 increased the anticancer effect of talazoparib via MUS81 inhibition in gastric cancer cells, and this combination effect was largely impaired when MUS81 was knocked down." (PMID 35480096, 2022). "Some researchers have found that the expression of MUS81 is downregulated in human hepatocellular carcinoma, gastric cancer, and colorectal cancer, and its SNP links to increased risks of breast cancer, but its expression was upregulated in ovarian cancer tissues." (PMID 35910852, 2022). "In this study, whether MUS81 silencing enhances talazoparib sensitivity, was evaluated in gastric cancer, and the mechanism of MUS81 knockdown sensitizing the anticancer effect of talazoparib was characterized." (PMID 35480096, 2022). "However, the therapeutic potential of targeting MUS81 in gastric cancer requires further exploration." (PMID 35480096, 2022).
gastric cancer (continued). "Our previous study reported that MUS81 was highly expressed and linked to tumor metastasis in gastric cancer; however, its therapeutic value has not been fully elucidated." (PMID 34625086, 2021). "MK1775 potently suppressed cell proliferation in a concentration-dependent manner and had a lower IC50 value in MUS81 knockdown gastric cancer cells than in MUS81 wild-type cells, and the 2D colony formation assay also showed less cell colony formation in MUS81 knockdown cells after MK1775 exposure." (PMID 34625086, 2021). "Our observations led us to next evaluate whether targeting MUS81 could elevate the anticancer effect of WEE1 inhibitors in gastric cancer cells." (PMID 34625086, 2021). "Although the WEE1 inhibitor MK1775 partly enhanced the anticancer effect of PD-L1 inhibitors by activating the cGAS/STING pathway, MUS81 targeting further amplified the anticancer effect of this combination strategy because of the elevated cytosolic dsDNA in gastric cancer cells." (PMID 34625086, 2021). "In addition, interfamilial cell co-culture showed that MK1775 exposure in MUS81 knockdown gastric cancer cells increased the early activation of CD8+ T cells." (PMID 34625086, 2021). "In addition, MK1775 treatment significantly increased the expression of proinflammatory cytokines such as CCL20, CXCL10, and IFN-β in MUS81 knockdown cells, but increased expression modestly in parental gastric cancer cells." (PMID 34625086, 2021). "Therefore, AZD5153 combined with talazoparib may represent a promising therapeutic strategy for patients with MUS81 proficient gastric cancer." (PMID 35480096, 2022). "Thus, it was hypothesized that AZD5153 might sensitize the talazoparib antitumor effect in gastric cancer cells by regulating MUS81 expression." (PMID 35480096, 2022). "Furthermore, using the MFC gastric cancer syngeneic mouse model we evaluated whether targeting MUS81 promoted the anticancer effect of MK1775 combined with ICB treatment in gastric cancer." (PMID 34625086, 2021). "Moreover, this may provide us a rational explanation as to why MUS81 inhibition alone had a limited effect on the proliferation of gastric cancer cells." (PMID 34625086, 2021). "Here, MUS81 inhibition increased the accumulation of cytoplasmic DNA induced by MK1775 treatment and activated the DNA sensor STING-mediated innate immunity in gastric cancer cells." (PMID 37354378, 2023). "Mechanistically, MUS81 inhibition impaired the activation of the ATR/CHK1 cell cycle signaling pathway and promoted gastric cancer cells with talazoparib-induced DNA damage to continue mitosis." (PMID 35480096, 2022). "The GO enrichment analysis showed that MUS81 might play an essential role in the immune response, and Gene Set Enrichment Analysis showed that MUS81 was negatively correlated with activation of the immune response in gastric cancer (P = 0.002, FDR q-value = 0.048)." (PMID 34625086, 2021). "In summary, we provided reliable data to demonstrate that MUS81 targeting amplified the activation of innate immune response and promoted the anticancer effect of WEE1 inhibitor and ICB combination therapy in gastric cancer." (PMID 34625086, 2021). "The expression of WEE1 showed limited change at the transcription level, but consistent with our observations in gastric cancer tissues, the WEE1 protein level was significantly elevated in MUS81 knockdown cells." (PMID 34625086, 2021). "In addition, it was observed that MUS81 knockdown reduced the activation of ATR and CHK1 in gastric cancer cells induced by talazoparib." (PMID 35480096, 2022). "With reference to the promising results from the anti-MUS81 therapy on gastric carcinoma, it would be interesting to know whether combining anti-MUS81 with anti-BPLF1 treatment would produce optimal anticancer effects in gastric carcinoma." (PMID 36802409, 2023).
gastric cancer (continued). "Furthermore, we performed IHC staining of specimens from a cohort of 26 patients with gastric cancer and observed a significant negative correlation between MUS81 and WEE1 kinase expression (Pearson r = −0.52, P = 0.0063)." (PMID 34625086, 2021). "Our study reports that MUS81 targeting could enhance the immune-modulating effect of WEE1 inhibitors, and this might promote new strategies and overcome obstacles during clinical treatment of patients with advanced gastric cancer." (PMID 34625086, 2021).